WAS (WASP actin nucleation promoting factor)
Diseases named in the same sentence as WAS in open-access papers (continued):
Sharing a sentence is not in itself a finding about the gene and the disease.
Wiskott-Aldrich syndrome (continued). "Furthermore, NK cells from patients with Wiskott-Aldrich Syndrome (WAS) who have mutations in the actin regulatory protein, WAS protein (WASp), are poorly cytotoxic." (PMID 21931536, 2011). "It is noteworthy that so far in our register there is no patient with a mutation in the WAS gene, given that the average incidence of Wiskott-Aldrich syndrome is between 1 and 10 cases per million boys." (PMID 36211402, 2022). "Similarly, Rajeev Rai succeeded in making the site-specific integration of a WAS cDNA in the WAS genomic locus in HSPCs, which has the potential to cure Wiskott-Aldrich syndrome." (PMID 37193354, 2022). "Wiskott-Aldrich syndrome (WAS) and X-linked congenital neutropenia (XLN) are severe immunodeficiency diseases caused by both LOF and GOF mutations in the Wiskott-Aldrich syndrome protein (WASp), respectively." (PMID 33987182, 2021). "We have previously shown that an MS-based approach for the quantification of signature peptides for BTK, WASP, and a T-Cell marker CD3ε from tryptic digests of PBMCs can be used to screen X-linked agammaglobulinemia (XLA), Wiskott-Aldrich Syndrome (WAS), and SCID, respectively." (PMID 32296420, 2020). "Wiskott-Aldrich Syndrome (WAS), has many clinical features seen in T cell immunodeficiencies, however, the X-linked gene defect affects WASP protein which is important for actin polymerization ensuring cytoskeletal integrity as well as signaling in all cells derived from the hematopoietic stem cell." (PMID 20465788, 2010). "Cytoskeletal disorders include Wiskott-Aldrich syndrome (WAS), Wiskott-Aldrich syndrome protein (WASP) WAP interacting protein (WIP), Dedicator of cytokinesis 8 (DOCK8) deficiency and Serine/threonine kinase 4 (STK4) deficiency." (PMID 37755421, 2023). "Wiskott-Aldrich syndrome (WAS) is an inherited condition caused by mutations in the WASP gene on the X chromosome, which encodes the WAS protein, an actin-nucleation promoting factor expressed in hematopoietic stem cells." (PMID 34682853, 2021). "Wiskott-Aldrich syndrome (WAS) is a rare X-linked primary immunodeficiency caused by absence of Wiskott-Aldrich syndrome protein (WASP) expression, resulting in defective function of many immune cell lineages and susceptibility to severe bacterial, viral, and fungal infections." (PMID 23141740, 2013). "Wiskott-Aldrich syndrome protein (WASp) is a cardinal NPF, first discovered as the protein encoded by a gene mutated in patients suffering from Wiskott-Aldrich syndrome (WAS)." (PMID 22837718, 2012). "In the most recent gene therapy trial for Wiskott-Aldrich Syndrome (WAS) an MLV-based vector backbone expressing the WAS protein was used for transduction of autologous CD34+ HSC which were transfused into two patients." (PMID 21994741, 2011). "The Arp2/3 complex is activated by the Wiskott-Aldrich Syndrome (WAS) family of proteins e.g., WASP, N-WASP and WASH, and primarily catalyses the nucleation of branched actin filaments." (PMID 40368919, 2025). "WASP is a hematopoietic-cell-specific NPF activated downstream of TCR, originally identified as a target of loss-of-function mutations in the X-linked immunodeficiency Wiskott-Aldrich syndrome (WAS)." (PMID 25758716, 2015). "Flow cytometric analysis for Wiskott-Aldrich syndrome protein (WASP) in lymphocytes in WAS patient." (PMID 21477322, 2011). "Abnormality of platelets in Wiskott-Aldrich syndrome (WAS) was studied in a mouse model lacking WAS protein." (PMID 33946341, 2021).
Immunodeficiency (54 papers, 2008 to 2026). Failure of the immune system to protect the body adequately from infection, due to the absence or insufficiency of some component process or substance. "Mutations in specific regions of the WAS gene, such as those affecting the VCA domain, can severely disrupt the function of WASp, impairing actin dynamics and leading to hallmark immunodeficiency and platelet abnormalities in WAS patients." (PMID 40821842, 2025). "Some patients with WAS mutations showed allergic proctocolitis, eczema, and immunodeficiency features, with initial misdiagnoses of cow milk protein-induced allergic proctocolitis in certain cases." (PMID 40488176, 2025). "A single patient harbored a harmful SNV in the WAS gene associated with immunodeficiency with congenital thrombocytopenia." (PMID 37592284, 2023). "For example, the first so called ‘actinopathy’, Wiskott–Aldrich syndrome (WAS) is characterised by immunodeficiency caused by loss-of-function mutations in the WAS protein (WASp), which regulates actin polymerisation." (PMID 35563720, 2022). "From a clinical standpoint, our study proposes WAS as a genotoxin-sensitive, genome-destabilizing immunodeficiency disorder that predisposes to cancer development, in part by mis-regulated RSR and DDR from the RPA defect." (PMID 35768435, 2022). "The first described so called “actinopathy” is Wiskott–Aldrich syndrome (WAS) in which patients suffer from severe immunodeficiency caused by loss-of-function mutations in the hematopoietic specific WAS protein (WASp)." (PMID 34422807, 2021). "Future studies will also be needed to clarify the ways in which the described mechanical deficits in the synapses formed by WASP‐deficient T cells contribute to the WAS immunodeficiency at the whole‐organism level." (PMID 31894880, 2020). "Wiskott–Aldrich syndrome (WAS) and X-linked neutropenia (XLN) are immunodeficiencies in which the function of several haematopoietic cell lineages is perturbed as a result of mutations in the actin regulator WASp." (PMID 23868979, 2013). "This pathology is characterized by mutations of the gene that encodes the WAS protein (WASp), and is characterized by immunodeficiency, thrombocytopenia, and eczema among others, and an increased risk to develop autoimmune disorders and malignancies, such as lymphoma." (PMID 40859612, 2026). "WAS gene affects platelet size and function, leading to low counts and immune deficiencies." (PMID 40822568, 2024). "WAS gene encodes WAS protein which has a role in regulation of actin polymerization by actin related protein complex The condition is characterised by the classical triad of severe immunodeficiency, eczema and micro thrombocytopenia." (PMID 36839544, 2023). "The variant and its effect on WAS protein expression determine the degree of immune deficiency." (PMID 36839544, 2023). "Therefore, the dysbiosis in WAS−/− mice appears coincident with the early immune dysfunction in the skin of WASp-deficient mice." (PMID 35265075, 2022). "Notably, another patient (HIES50) clinically diagnosed with HIES was shown to have a hemizygous mutation in WAS (p.P403L), which had previously been published as causing mild immunodeficiency, muscle dystonia, and thrombocytopenia." (PMID 34390440, 2021). "WAS, which is a severe X-linked immunodeficiency, is caused by mutations in WAS protein (WASP) gene; the clinical manifestations include eczema, immunodeficiency, thrombocytopenia with small platelets, and an increased risk of developing autoimmunity and malignancies." (PMID 24198970, 2013). "Combined immunodeficiencies alongside syndromic characteristics were associated with pathogenic mutations in DOCK8, STAT3, WAS, ATM, and TBX1, which included an autosomal dominant STAT3 variant (c.1144C>T; p.Arg382Trp) and an X-linked WAS variant (c.271C>T)." (PMID 40806973, 2025). "WAS is the first in a growing list of genes whose disruption result in immunodeficiencies that are due to cytoskeletal abnormalities." (PMID 24117828, 2013).
Immunodeficiency (continued). "WAS manifests as an immune deficiency characterized by eczema, thrombocytopenia, recurrent infections, and hematopoietic malignancies, demonstrating the importance of WIP for WASp complex formation and for a proper immune response." (PMID 22837718, 2012). "A human WIP deficiency, caused by a stop codon mutation in the WIP coding gene, causes an immunodeficiency disease with similar characteristics to those of WAS, including an undetectable level of WASp expression." (PMID 22837718, 2012). "Notably, mutations in WAS, WIPF1 or DOCK8 have been reported in human immunodeficiencies, underscoring the importance of these cytoskeleton regulators during immune responses." (PMID 29337666, 2018). "WASP is indispensable for normal leukocyte function and its importance is highlighted in the congenital disorder Wiskott–Aldrich syndrome in which missense mutations in the WAS gene result in severe immunodeficiency." (PMID 25413351, 2015). "The discovery of WASP protein evolved from the study of Wiskott–Aldrich syndrome; it is an X-linked autosomal recessive disorder due to mutation in the WAS gene and is characterized by recurrent infection due to immune deficiency, microthrombocytopenia and eczema." (PMID 34572403, 2021). "Combined with the low expression of WASp, the analytical results of lymphocyte subsets further demonstrated that significant WASp deletion could lead to T cell deficiency, which is a key factor in WAS-associated immune dysfunction." (PMID 33879693, 2021). "Reduced or absent WASp expression may result in the primary immunodeficiency disorder Wiskott–Aldrich Syndrome (WAS), which is characterized by a classical triad of microthrombocytopenia, eczema and immune deficiency, affecting 1–10 in 1 000 000 live births." (PMID 19628299, 2009). "WAS is a combined immunodeficiency disorder characterized by thrombocytopenia, and it primarily affects males with dysfunctional platelets due to defects in the WAS protein (WASp) that lead to bleeding problems and severe recurrent infections, with an incidence rate of between 1 and 10 in 1 million." (PMID 39846592, 2025). "As expected, our study identified several well-known PADs such as STAT3, WAS, DOCK8, SPINK5, and CARD11 that are classified according to the IUIS as combined immunodeficiency with or without syndromic features." (PMID 35273610, 2022).
Thrombocytopenia (47 papers, 2008 to 2026). A reduction in the number of circulating thrombocytes. "In the present study, we investigate the pathogenic role of a splice site variant of uncertain significance (VUS) in the WAS gene, identified in a 2-month-old boy with thrombocytopenia and immunological alterations." (PMID 39917307, 2025). "All patients had a confirmed genetic mutation in the WAS gene and presented with symptoms related to classic WAS such as thrombocytopenia, eczema, and recurrent infections." (PMID 36044170, 2023). "Variants of the WAS gene lead to Wiskott–Aldrich syndrome, an X-linked recessive immunodeficiency characterized by thrombocytopenia, eczema and recurrent infections (#301000)." (PMID 37628571, 2023). "In this disease, loss-of-function pathogenic variants of WAS are responsible for cytoskeletal defects of megakaryocytes (and thus thrombocytopenia), decrease in T-cell migration, B and T cell leukopenia, defective NK cells, and neutropenia." (PMID 38250061, 2023). "Mutations in the WAS gene on the X chromosome, which encodes the WAS protein (WASP), are a cause of Wiskott–Aldrich syndrome, characterized by recurrent infections, thrombocytopenia with small platelets, and eczema." (PMID 35887984, 2022). "For male patients who present with congenital thrombocytopenia and small platelets, it is necessary to assess WAS gene mutation and WASp expression by the molecular genetic approach and protein detection as early as possible." (PMID 33879693, 2021). "The syndrome, the result of mutations in the WAS gene which encodes the Wiskott-Aldrich protein (WASp), has wide clinical phenotype variation, ranging from classical WAS to X-linked thrombocytopaenia and X-linked neutropaenia." (PMID 32503528, 2020). "Among these, GP1BA (c.1591dup, c.1525C>T, and c.378C>G), ITGB3 (c.1394C>G), NBEAL2 (c.3796del), WAS (c.655G>T, deletions of exons 1-2), and MPL (c1511T>A) were notable for their association with severe thrombocytopenia and morphological platelet abnormalities." (PMID 40488176, 2025). "The patient presented with persistent thrombocytopenia with small platelets and decreased WAS protein detected by flow cytometry and western blot analysis." (PMID 34307257, 2021). "We identified a WAS splice site VUS in a 2-month-old boy presenting with thrombocytopenia." (PMID 39917307, 2025). "There is a strong genotype/phenotype correlation in WAS, with WASP- (complete absence) resulting in a classic WAS, and WASP+ (residual protein expression) resulting in the minor clinical phenotype of X-linked thrombocytopenia (XLT) with only minor eczema and thrombocytopenia." (PMID 36726976, 2022). "Full reconstitution of WASp expression could also contribute to more reliable correction of thrombocytopenia, and therefore to application of this approach to patients with attenuated WAS who predominantly manifest thrombocytopenia and bleeding risk." (PMID 32788576, 2020). "WASp defect particularly causes platelets abnormality which is presented in forms of decrease of Mean Platelet Volume (MPV) and thrombocytopenia in most WAS conditions; nevertheless, some studies reported WAS patients with a normal or large size of platelets in recent years." (PMID 31379999, 2019). "Knockout of MKL1 in mice results in megakaryocyte maturation defects and thrombocytopenia, and may therefore mimic some aspects of WAS 243,244." (PMID 24117828, 2013). "The thrombocytopenia in WIP deficiency seems to be less severe and inconstant, and microthrombocytopenia is less frequent than in WAS, raising the question whether other molecules could substitute for WIP as chaperones for WASP specifically in platelets and megakaryocytes." (PMID 30450104, 2018). "This leads to altered or absent WAS protein (WASp) expression and function resulting in thrombocytopenia, eczema, recurrent infections, and autoimmunity." (PMID 37350958, 2023).
Thrombocytopenia (continued). "By labeling a few proteins, a potential abnormality could be identified or narrowed-down to a group of IPDs featured by cytoskeleton alterations (e.g., FLNA-related thrombocytopenia, FLNA-RT, TUBB1-related thrombocytopenia, TUBB1-RT, and WAS)." (PMID 32079152, 2020). "Thrombocytopenia was observed in all 31 children enrolled in the study, including those with a confirmed molecular diagnosis of WAS/XLT (22 patients) and those with negative WAS gene and WIPF1 gene sequencing results (9 patients)." (PMID 40821842, 2025). "For MYH9, this could be partially explained by exceptional size increase (it was also the only thrombocytopenia except for ITP with increased CD62p), but not for WAS." (PMID 33931737, 2021). "A female patient with the classical symptoms of WAS, including eczema, thrombocytopenia, recurrent infections, defective T-cell proliferation and chemotaxis, and impaired NK cell function was found to have normal WAS gene sequence and mRNA levels but a complete absence of WASp expression." (PMID 24117828, 2013).
Autoimmunity (31 papers, 2010 to 2025). The occurrence of an immune reaction against the organism's own cells or tissues. "Other actin regulatory genes expressed in hematopoietic cells are mutated in autoimmune disorders beyond WAS and ARPC1B deficiency." (PMID 34673575, 2021). "WAS is frequently associated with autoimmunity, indicating a critical role of WASp in maintenance of tolerance." (PMID 28512459, 2017). "The role of WASp deficiency in the development of autoimmunity in WAS has been explored extensively." (PMID 26448644, 2015). "Mutations in WAS are associated with distinct clinical phenotypes, and mutations that significantly affect WAS protein function lead to the most severe phenotype, which is further complicated by autoimmunity and malignancies." (PMID 21477322, 2011). "WAS protein deficiency underlies a severe human condition characterized by recurrent infections and autoimmunity caused at least in part by perturbed leukocyte migration toward chemotactic cues." (PMID 21176202, 2010). "All these data in our study were insufficient to prove a direct association between the alteration of WAS TCR diversity and autoimmunity." (PMID 35116029, 2021). "The high incidence of autoimmunity in WAS patients indicates a critical role of WASp in the maintenance of central and peripheral tolerance." (PMID 28512459, 2017). "Nevertheless, impairment in both regulatory activities of WASP on T cell death can be related to immunodeficiency and autoimmunity in WAS patients." (PMID 25709608, 2015). "WAS involves intrinsic B cell defects that lead to autoimmunity." (PMID 34673575, 2021). "Our observations uncovered additional characteristics of the defective compartment of regulatory B cells that develops in the absence of WASp expression and provides possible insights into the development of autoimmunity with increasing age in patients affected with WAS." (PMID 26448644, 2015). "Similarly, increased autoantibody production and autoimmunity have been demonstrated in two models of B-cell-selective WASp deficiency suggesting that there is a B-cell intrinsic role in WAS-related autoimmunity 28,43." (PMID 24945741, 2014). "We therefore postulated that deficiency of Breg-cell function may contribute significantly to the autoimmune phenotype of WAS and used an experimental model of antigen-induced arthritis to investigate the contribution of Breg cells to WAS-related autoimmunity." (PMID 24945741, 2014). "Here, we have used an experimental arthritis model to investigate autoimmunity in WAS KO mice." (PMID 24945741, 2014). "Since iNKT cells are reduced in WAS patients and functionally defective in Was−/− mice it can be hypothesized that such impairment may also contribute to autoimmunity." (PMID 22826711, 2012). "Some organ-specific autoimmune disorders were observed in these patients including hematologic autoimmunity in patients with PNP, STIM1, ORAI1, WAS, ATM, and STAT5B mutations or early-onset inflammatory bowel disease in patients with WAS, DNMT3B, and ZBTB24 mutations." (PMID 36544766, 2022). "The frequency of autoimmunity was high among patients with RAG, WAS, STAT5b, NF-κB2, Fas, FasL, LRBA, APECED, IL-10, and C4 deficiencies." (PMID 32582199, 2020). "Interestingly, selective deficiency of WASp in Breg cells appears to be compensated by intact functionality in other regulatory lineages, suggesting that partial restoration of regulatory cell function in WAS may be sufficient to protect or alleviate autoimmunity." (PMID 24945741, 2014). "A comprehensive comparison in terms of demographic, clinical, and immunological features was performed between patients with and without autoimmunity and also among four mutation groups with the most registered cases including ATM, STAT3 (AD-LOF), DNMT3B/ZBTB24, and WAS mutations." (PMID 36544766, 2022).
Autoimmunity (continued). "The contribution of external factors to the development of autoimmunity could indeed be critical for WAS patients and could explain the high variability in the frequency of these manifestations, ranging from 25 to 72%, regardless of WASp expression." (PMID 28512459, 2017).
eczema (30 papers, 2012 to 2026). "Indeed, it has been shown that WAS patients with residual WASP expression develop moderate or transient form of the disease, whereas most of WASP-negative patients develop severe, treatment-resistant eczema." (PMID 22826711, 2012). "WAS T-cell lines have a selective defect in TH1 cytokine production, and WASP-deficient mice develop a skewed TH2 phenotype, supporting the hypothesis that eczema and high IgE in patients with WAS are related to a TH2 imbalance." (PMID 31354712, 2019).